PTX3 (pentraxin 3)
Diseases named in the same sentence as PTX3 in open-access papers (continued):
Sharing a sentence is not in itself a finding about the gene and the disease.
diabetes (34 papers, 2012 to 2025). "In this study, we studied the mechanisms underlying the PTX3 deficiency-mediated antidiabetic effects of pancreatic β-cell in a mouse model of STZ-induced diabetes." (PMID 39657836, 2025). "The most significant predictors of death in the regression analysis were hypertension (OR 14.0), diabetes (OR 3.87), PTX3 (OR 1.57), and ACE D/D polymorphism (OR 2.96)." (PMID 39062191, 2024). "Our findings revealed that PTX3-deficient mice were protected from visual impairment induced by diabetes." (PMID 39348530, 2024). "In summary, PTX3 deficiency during diabetes contributed to preservation of visual function and delay of neurodegeneration, without affecting HbA1c levels." (PMID 39348530, 2024). "In another multicentric study (CAPIRE) (including patients with coronary calcium), HRP were associated with male sex, older age, diabetes and biomarkers of inflammation such as c-reactive protein and PTX-3." (PMID 36140444, 2022). "After adjustment with sex, age, diabetes mellitus, and plasma PTX3 concentration, miR-224-3p ≥ median group was associated with angiographic MVO (odds ratio, 2.60; 95% confidence interval, 1.24 to 5.44, p = 0.01)." (PMID 33121529, 2020). "More than 70% of diabetic patients took medications for diabetes mellitus, suggesting that these treatments affected the association between plasma PTX3 levels and diabetes mellitus in our study population." (PMID 24705587, 2014). "Elevated PTX3 levels have been associated with an increased risk of CV events and may serve as a useful marker for vascular inflammation in diabetes-related heart disease." (PMID 40299501, 2025). "In our study, PTX3 was a more powerful predictor than traditional risk factors, including smoking, hypertension, diabetes mellitus, statin use and high density lipoprotein for carotid artery stenosis with ischemic stroke, based on logistic binary regression analysis." (PMID 31998222, 2019). "In addition, PTX3 wasn’t associated with BMI, existence of hypertension or dyslipidemia, duration of hypertension or diabetes, smoking, serum creatinine level, max IMT, baPWV and the use of each drug or the number of anti-hypertensive drugs." (PMID 29715313, 2018). "It has recently also been found that plasma levels of pentraxin 3 (PTX3, an acute phase reactant which reflects impaired vascular endothelial function) are associated with the development and progression of DR in Korean patients with Type 2 diabetes mellitus." (PMID 27313539, 2016). "Other unresolved issues include which metabolic components mainly associate with plasma PTX3 levels; whether plasma PTX3 levels correlate with insulin resistance or diabetes mellitus; and the association of PTX3 with other inflammatory markers." (PMID 24705587, 2014). "We further explored the association between PTX3, metabolic syndrome, and diabetes mellitus." (PMID 24705587, 2014). "The mean PTX3 level in the non-diabetes group was 2150 ± 1040 pg/mL, whereas in the diabetes group, the PTX3 level was higher, at 3200 ± 1910 pg/mL." (PMID 40299501, 2025). "Chronic exercise training has been shown to reduce PTX3 levels in individuals with diabetes while increasing PTX3 levels in healthy individuals, ultimately leading to similar PTX3 levels between both groups." (PMID 41562853, 2025). "A paired t-test compared pre- and post-dialysis vitamin C and PTX3 levels, stratified by comorbidities (diabetes mellitus and hypertension)." (PMID 40470435, 2025). "The implications of these findings extend beyond our understanding of PTX3's role in diabetes mellitus to its potential as a therapeutic target." (PMID 39657836, 2025). "PTX3 has emerged as a significant marker of vascular inflammation and metabolic complications in diabetes." (PMID 40299501, 2025). "The findings underscore the significance of PTX3 as a potential therapeutic target for diabetes mellitus and highlight the need for further research to elucidate its precise mechanisms of action and therapeutic implications." (PMID 39657836, 2025).
diabetes (continued). "This study identifies a role for Pentraxin 3 (PTX3) in driving various pathological features in the diabetic retina." (PMID 39348530, 2024). "To further understand the role of PTX3 within DR, we employed the streptozotocin-induced diabetes model in PTX3 knockout mice (PTX3KO), which were followed up for 9 mo to evaluate hallmarks of disease progression." (PMID 39348530, 2024). "In this study, we assessed the expression of PTX3 in the diabetic retina and investigated how PTX3 affects retinal cell biology during diabetes, using a 9-mo diabetes mouse model and human retinal cells in vitro." (PMID 39348530, 2024). "Taken together, these results are suggestive of a key role for PTX3 in retinal microglia activation during diabetes." (PMID 39348530, 2024). "Our data also provide mechanistic insight into the role of PTX3 in the proinflammatory retinal microenvironment as diabetes progresses." (PMID 39348530, 2024). "After 9 mo of diabetes, eyeballs were sampled, and retinas were processed for laser confocal microscopy after immunostaining with PTX3 antibody." (PMID 39348530, 2024). "In light of all this evidence, we suggest that PTX3 functions at the crossroads of inflammation and diabetes." (PMID 39348530, 2024). "To investigate the inflammatory hallmarks in diabetic retinas, we used the STZ-induced diabetes mouse model in PTX3 wild-type (WT) and knockout (PTX3KO) mice." (PMID 39348530, 2024). "In the mouse retina, we found PTX3 protein accumulation in the nerve fiber, outer nuclear, and outer plexiform layers, but only at 9-mo diabetes." (PMID 39348530, 2024). "The secondary genes TNFAIP, MMP9, and CXCL showing interaction with PTX3 have a potential role in diabetes mellitus." (PMID 36051390, 2022). "Further, elevated PTX3 have also been reported in people with ventricular dysfunction, atrial fibrillation, and diabetes mellitus which are comorbidities present in our study population." (PMID 38560419, 2022). "As based on results from univariate analysis, serum PTX3 levels, diabetes mellitus, discharge NIHSS score and a intracranial artery stenosis of ≥50% were identified as predictors for an unfavorable outcome." (PMID 33210471, 2021). "As based on univariate analysis, serum PTX3 levels, diabetes mellitus, discharge NIHSS score, and serum LDL cholesterol (LDL‐C) were predictors for an unfavorable outcome in this LAA subgroup." (PMID 33210471, 2021). "Variables included into the multivariate analysis were age, sex, diabetes mellitus, miR-155-5p and miR-224-3p expressions, and plasma PTX3 concentration." (PMID 33121529, 2020). "We consider that oxidative stress is a common regulative factor on PTX3 in these diseases including diabetes and PA." (PMID 29715313, 2018). "We also found that serum PTX3 level was significantly positively correlated with existence of diabetes, HbA1c and UAE in this study (r = 0.379, P<0.001; r = 0.431, P<0.001; r = 0.313, P = 0.009)." (PMID 29715313, 2018). "We have shown the significant correlation between PTX3 and existence of diabetes, HbA1c, UAE, PAC and high-sensitive CRP in total population of this study." (PMID 29715313, 2018). "Serum PTX3 levels were measured in 75 patients (45 male and 30 women, aged 55.1±13.4 year-old (mean±SD)) with various endocrine disorders including 47 with diabetes, 24 with primary aldosteronism (PA)." (PMID 29715313, 2018). "Actually, it was shown that serum PTX3 level was positively correlated with atherosclerotic markers in patients with diabetes." (PMID 29715313, 2018). "Taken together, to the best of our knowledge, our study is the first to demonstrate α-synuclein accumulation in the cerebellum and increased plasma PTX3 levels in the STZ-induced diabetes model." (PMID 28133547, 2017).
diabetes (continued). "Moreover, when comorbidities that could influence inflammatory response (i.e., diabetes, tumors, and/or respiratory diseases) were included in the Charlson’s Index, PTX3 level associates positively with the Charlson’s Index (beta = 0.15; p = 0.005, data not shown)." (PMID 28536575, 2017). "High PTX3, PCT, age over 60 years, alcohol abuse, diabetes and continuous systemic cortisone treatment were associated with case fatality (d28) in the univariate model while the level of CRP was not (data not sown)." (PMID 23341967, 2013). "Although the present study demonstrated that a clinical history of CVD conferred higher circulating PTX3 and SAT PTX3 mRNA levels in CKD patients, these associations were lost after adjusting for age, sex, diabetes and ADMA (or Arginine/ADMA)." (PMID 23658833, 2013). "Additionally, PTX3 levels tend to be higher in individuals with diabetes and lower in healthy individuals." (PMID 41562853, 2025). "This again illustrates PTX3’s context-specific behavior: elevated levels in diabetes may reflect pathological inflammation, whereas increases induced by exercise likely support metabolic regulation and tissue protection." (PMID 41562853, 2025). "Given the observed protective effects of PTX3 deficiency against STZ-induced deformation of pancreatic islets and β-cell death, targeting PTX3 may represent a promising strategy for mitigating diabetes-related complications." (PMID 39657836, 2025). "Moreover, PTX3 has the ability to bind harmful molecules, such as advanced glycation end-products (AGEs), which are elevated in individuals with diabetes, and acts as an antioxidant and anti-inflammatory agent." (PMID 41562853, 2025). "This could be due to the fact that PTX3 has been demonstrated as a marker of vascular disease and metabolic syndrome, which are presented by the majority of patients with diabetes." (PMID 37510110, 2023). "First, in this study, PTX3 was positively correlated with existence of diabetes and HbA1c." (PMID 29715313, 2018). "We considered that we could not evaluate the progression of macro-vascular damage among patients with PA or diabetes by using PTX3." (PMID 29715313, 2018). "Furthermore, a stepwise multiple regression analysis was performed between PTX3 and each parameter which was correlated with serum PTX3 level in univariate model, such as existence of diabetes, HbA1c, UAE, PAC, high-sensitivity CRP." (PMID 29715313, 2018). "This is in agreement with the positive relationship between PTX3 and the Charlson’s Index observed when conditions significantly impacting the inflammatory response, i.e., diabetes, tumors, and/or respiratory diseases, were included in the analysis (data not shown)." (PMID 28536575, 2017). "Nevertheless, further research on PTX3 expression and diabetic phenotypes in larger groups of diabetic patients matched for diabetes duration, age and sex may still be motivated." (PMID 23658833, 2013). "In conclusion, due to increased inflammation and neurotoxicity in the chronic period of hyperglycemia linked to diabetes, there may be α-synuclein accumulation in the cerebellum and the plasma MDA, GSH, and PTX3 levels may be assessed as important biomarkers of this situation." (PMID 28133547, 2017). "Senescence proteins CKAP4 and PTX3 were shown to be capable of distinguishing AKI and CKD patients from a comorbid control cohort including patients with diabetes, CVD, and RA." (PMID 39404377, 2024). "High-resolution microscopy allowed PTX3 protein to be localized in the nerve fiber (NFL), outer plexiform (OPL), and outer nuclear (ONL) layers in wild-type retinas 9 mo after diabetes induction." (PMID 39348530, 2024). "Duration of diabetes, body mass index, serum HbA1c, vascular endothelial growth factor (VEGF), APN, pentraxin 3 (PTX3), platelet derived growth factor (PDGF), intercellular adhesion molecule-1 (ICAM-1), and APN were measured and analyzed." (PMID 34780524, 2021).
diabetes (continued). "Multivariate linear regression was performed to study the interaction of PTX3 with age, gender, smoking history, family history of cerebrovascular disease, BMI, level of TNF-α, CHOL, TG, HDL, hs-CRP, hypertension, diabetes mellitus, and history of statin use." (PMID 31998222, 2019). "Then, our study newly revealed that PTX3 was negatively correlated with PAC and the correlation was also shown in patients with diabetes." (PMID 29715313, 2018). "In patients who are obese and who have diabetes, tumor necrosis factor-α (TNF-α) can induce an increase in PTX3 in smooth muscle cells (HASMC) through the MAPK pathway in response to inflammation." (PMID 28770376, 2017). "Nevertheless, PTX3 was elevated in the aqueous humor of patients with diabetes when compared to the nondiabetic cohort." (PMID 39348530, 2024). "PTX3 mRNA expression in whole murine retinal isolates showed a significant increase at 9-mo after diabetes induction, when compared to nondiabetic age-matched retinas." (PMID 39348530, 2024). "This evidence indicated that PCT, 25(OH)D, PTX-3, and AMS could be indicators for diabetic ketoacidosis with pancreatitis." (PMID 34187463, 2021). "Serum PTX3 level was significantly lower in patients with PA than without PA and was significantly higher in patients with diabetes than without diabetes." (PMID 29715313, 2018). "In addition, PTX3 was significantly correlated with triglyceride and 8-epi-PGF2α in patients with PA, and with triglyceride and PAC in patients with diabetes." (PMID 29715313, 2018). "Compared to patients with a healthy weight (BMI <25), both overweight patients (25≤ BMI <30) and obese patients (BMI ≥30) had lower mean plasma PTX3 levels among those without diabetes (n = 655), after adjustment for confounders." (PMID 24705587, 2014). "Among individuals without diabetes, obese individuals had lower plasma PTX3 levels than lean individuals." (PMID 24705587, 2014). "In this study population, individuals with diabetes had higher plasma PTX3 levels than non-diabetic individuals although PTX3 did not correlate with fasting glucose, insulin or the HOMA-IR." (PMID 24705587, 2014). "Conversely, patients with diabetes (mean = 4.53 ng/mL, SE = 0.11) had higher adjusted mean PTX3 concentrations than did controls without diabetes (mean = 3.96 ng/mL, SE = 0.07)." (PMID 24705587, 2014). "Moreover, the observed associations, positive and inverse respectively, between SAT PTX3 mRNA levels and elevated ADMA levels (adjusted for age, sex and diabetes mellitus) and ex vivo resistance artery constriction, were also restricted to CKD." (PMID 23658833, 2013). "In a multivariate model, plasma PTX3 was a significant predictor of PTX3 mRNA independent of age, sex and diabetes." (PMID 23658833, 2013). "This increase in PTX3 was not apparent at 3 mo and 6 mo of experimental diabetes." (PMID 39348530, 2024). "These significant correlations with PTX3 weren’t shown in patients with PA nor diabetes." (PMID 29715313, 2018). "Finally, serum PTX3 level was higher in patients without PA or with diabetes than with PA or without diabetes (P = 0.006, P = 0.003)." (PMID 29715313, 2018). "Because the control of blood glucose was poor in patients with diabetes whose mean HbA1c was 9.1±2.3%, we could not observe the relationship between PTX3 and 8-epi-PGF2α in total population or patients with diabetes." (PMID 29715313, 2018). "However, multivariate regression analysis, including age, sex and PTX3 plasma levels, showed no independent association between diabetes status and SAT PTX3 mRNA expression." (PMID 23658833, 2013). "On the other hand, PTX3 was not significantly correlated with HbA1c and UAE but significantly negatively correlated with PAC in patients with diabetes." (PMID 29715313, 2018). "Significantly higher PTX3 levels were noted in patients with AHF, acute kidney injury, diabetes mellitus, and nonhypercholesterolemic patients." (PMID 25922551, 2015).
prostate carcinoma (31 papers, 2014 to 2025). A carcinoma that arises from epithelial cells of the prostate gland. "Adjusted odds ratio (AOR) and 95% confidence interval (CI) of prostate cancer associated with PTX3 genotypic frequencies." (PMID 39187920, 2024). "Particularly, calcifications in normal and cancerous tissue in the breast, in prostate cancer and in atheromas are associated with high PTX3 expression." (PMID 36138045, 2022). "In previous observations, our research group demonstrated that an increased expression of PTX3 was related to diagnosis of prostatic cancer and to an increased risk of prostate cancer development, if assessed in patients undergoing prostate biopsy." (PMID 32345771, 2020). "In this experimental model, PTX3-expressing TEMs were able to efficiently deliver the PTX3 protein to the tumor site in a syngeneic FGF2-dependent model of prostate cancer, causing a significant reduction of the growth of the tumor grafts." (PMID 30349543, 2018). "In prostate cancer, PTX3 showed an association with the increased early component of the complement system and a complement inhibitor, CD59, and the authors speculated that the change in inflammatory signal possibly promoted the oncogenic process." (PMID 39594709, 2024). "Moreover, the results of studies on prostate cancer demonstrate a strong association between high PTX3 expression and tumor metastasis." (PMID 39594709, 2024). "Their results underline the utility of PTX-3 as a discriminating factor of benign prostatic hyperplasia from cancer, at the cut-off value of 3.25 ng/mL (88.5% specificity and 89.3% sensitivity) and also as potential quantifying factor for prostatic cancer risk development." (PMID 36499628, 2022). "In particular, we studied whether increased PTX3 expression was associated with Complement cascade activation and whether the latter event may be related with progression from chronic prostate inflammation to prostate cancer." (PMID 33110136, 2020). "In essence, this study suggests that PTX3, a potential biomarker for distinguishing prostate cancer from BPH, promotes tumor progression by inhibiting the activation of the terminal complement pathway through increased CD59 expression." (PMID 41479916, 2025). "The PTX3 is highly expressed in high-grade prostate cancer lesions, and is positively correlated with 18F-choline uptake." (PMID 41479916, 2025). "PTX3 positive cells in prostate tumors are increased compared to benign lesions, and show an inverse correlation with the number of PD-L1 positive prostate cancer cells." (PMID 41479916, 2025). "PTX3 levels are higher in the tumor lesions and serum of prostate cancer patients compared to those with prostatic inflammation/BPH, and increase progressively over time." (PMID 41479916, 2025). "PTX3 is upregulated in prostate cancers at both mRNA and protein levels, and is positively correlated with expression of ERα and EGFR." (PMID 41479916, 2025). "They found that PTX3 was overexpressed in prostate cancer compared to benign lesions, suggesting its potential role in tumor progression." (PMID 41479916, 2025). "PTX3 inhibits dihydrotestosterone- or FGF8b-driven mitogenic activity in androgen-regulated human prostate cancer cells." (PMID 41479916, 2025). "Odds ratios (ORs) and 95% confidence intervals (CIs) of the clinical status and PTX3 rs2305619 and rs1840680 genotypic frequencies in 705 patients with prostate cancer." (PMID 39187920, 2024). "Odds ratios (ORs) and 95% confidence intervals (CIs) of the clinical status and PTX3 rs3816527 genotypic frequencies in 705 patients with prostate cancer with different age at diagnosis." (PMID 39187920, 2024). "These protumoral effects of PTX3 have also been demonstrated in experiments with pancreatic, stomach, breast, cervical, high-grade brain, and prostate cancer cell lines." (PMID 39594709, 2024).